IFITM5 (interferon induced transmembrane protein 5)
Description:
Required for normal bone mineralization.
Synonyms: BRIL; DSPA1; fragilis4; Hrmp1; OI5
Tractability: Antibody: UniProt places it where antibodies can reach, with high confidence; its Gene Ontology location is reachable by antibodies, with high confidence; UniProt predicts a signal peptide or a membrane-spanning region; the Human Protein Atlas places it where antibodies can reach.
Gene: Protein-coding gene on chromosome 11 (298,200 to 299,526, reverse strand). Ensembl gene ENSG00000206013.
Subcellular location: Cell membrane
Subcellular location (Human Protein Atlas): Plasma membrane; Cytosol; Vesicles
Gene Ontology:
Biological process: bone mineralization; bone morphogenesis; in utero embryonic development
Cellular component: plasma membrane; membrane
Genetic constraint (gnomAD): Loss-of-function variants: 10 observed, 8.4 expected, observed/expected ratio (o/e) 1.19, 90% interval 0.73 to 1.83. That is too few expected variants to judge how well the gene tolerates losing a copy. Missense variants: 225 observed, 171.92 expected, observed/expected ratio (o/e) 1.31, 90% interval 1.17 to 1.46. Synonymous variants: 93 observed, 78.77 expected, observed/expected ratio (o/e) 1.18, 90% interval 1 to 1.4.
Homologues: Orthologues: chimpanzee IFITM5 (99% identical), macaque IFITM5 (98% identical), pig IFITM5 (90% identical), dog IFITM5 (89% identical), guinea pig IFITM5 (84% identical), rat Ifitm5 (81% identical), mouse Ifitm5 (80% identical), tropical clawed frog ifitm5 (51% identical), zebrafish ifitm5 (44% identical). Paralogues in human: IFITM3 (30% identical), IFITM2 (29% identical), IFITM1 (28% identical), IFITM10 (25% identical).
Diseases named in the same sentence as IFITM5 in open-access papers:
IFITM5 is named in the same sentence as 26 diseases in open-access papers, as found by Europe PMC text mining. Sharing a sentence is not in itself a finding about the gene and the disease. The quoted sentences say what the papers report.
osteogenesis imperfecta (16 papers, 2014 to 2024). Osteogenesis imperfecta (OI) comprises a heterogeneous group of genetic disorders characterized by increased bone fragility, low bone mass, and susceptibility to bone fractures with variable severity. "There are other examples of lethality in heterozygous mice with constitutively expressed mutations, such as one with a missense mutation knocked into Ifitm5, which, in humans, causes type V osteogenesis imperfecta." (PMID 38967226, 2024). "There are already proven cases published about osteosarcoma occurring in osteogenesis imperfecta due to IFITM5 mutation." (PMID 36759884, 2023). "The method was described earlier to characterize OLS in OI type V, a distinct form of osteogenesis imperfecta caused by a gain-of-function mutation in the IFITM5 gene." (PMID 33925942, 2021). "Type V of OI is unique among all types of osteogenesis imperfecta: most patients (approximately 95%) with type V have the same heterozygous mutation in IFITM5, a point mutation in 5′-UTR (c.-14C>T), which generates a new starting codon and adds five residues to the N–terminal end of the protein." (PMID 35052464, 2022). "Osteogenesis imperfecta (OI) type V is an autosomal dominant disorder caused by the c.-14C > T mutation in the interferon-induced transmembrane protein 5 gene (IFITM5), however, its onset mechanism remains unclear." (PMID 33273604, 2020). "The genetic mutation resulting in osteogenesis imperfecta (OI) type V was recently characterised as a single point mutation (c.-14C > T) in the 5’ untranslated region (UTR) of IFITM5, a gene encoding a transmembrane protein with expression restricted to skeletal tissue." (PMID 24674092, 2014). "Among the functional ontologies, only IFITM5 played a crucial role in the process of OS oncogenesis, including osteogenesis imperfecta, and decreased bone thickness, volume, and length." (PMID 36759884, 2023). "Recently, an atypical case of osteogenesis imperfecta type VI was reported in which the patient had normal serum PEDF levels and correct SERPINF1 gene sequence, but a heterozygous single point mutation in the IFITM5 gene." (PMID 25881671, 2015). "Why this mutation in IFITM5 affects PEDF expression and secretion and how it leads to osteogenesis imperfecta type VI remains unknown." (PMID 25881671, 2015). "Following reports stating that no major abnormality is seen in the osteogenesis of Ifitm5-deficient mice, many research groups have reported that patients with osteogenesis imperfecta (OI) type V have a heterozygous point mutation (c.-14C > T) in the 5 ' untranslated region of the IFITM5 gene." (PMID 33273604, 2020).
osteogenesis imperfecta type 5 (9 papers, 2014 to 2025). Osteogenesis imperfecta type V is a moderate type of osteogenesis imperfecta (OI), a genetic disorder characterized by increased bone fragility, low bone mass and susceptibility to bone fractures with variable severity. "Genetic studies have confirmed that type V OI was caused by a point mutation in the 5′ UTR of IFITM5 gene (c.-14C>T), resulting in the addition of 5 amino acids (Met-Ala-Leu-Glu-Pro, MALEP) at its N-terminus." (PMID 39908237, 2025). "Mice expressing the mutant Ifitm5 allele are viable and recapitulate the low bone mass and exuberant cartilage formation that is observed in humans with OI type V." (PMID 38885336, 2024). "We have previously generated a transgenic mouse model by overexpressing Ifitm5 cDNA with the novel start codon, corresponding to the recurrent human OI type V mutation, under the control of the Col1a1 2.3 kb promoter." (PMID 38885336, 2024). "Consistent with the observations in OI type V mouse models, expression of mutant IFITM5 in MC3T3 cells was associated with increased ERK phosphorylation and delayed mineralization in vitro." (PMID 38885336, 2024). "Given the high phenotypic variability of OI type V and the fact that all patients have the same IFITM5 mutation, this would present an ideal condition under which to search for modifier genes in the next-generation sequencing era." (PMID 36289625, 2022). "In this study, we examined the clinical features of twelve individuals from twelve unrelated families diagnosed with OI type V and identified a pathogenetic c-14C>T mutation in the IFITM5 gene." (PMID 36289625, 2022). "This study aimed to chart clinical and genetic characteristics of OI type V with identified pathogenic changes in the IFITM5 gene in patients from Russia." (PMID 36289625, 2022). "A breakthrough in the diagnosis of OI type V occurred in 2012 when a mutation in the IFITM5 gene was first identified and described." (PMID 36289625, 2022). "We sampled twelve patients with OI type V with an identified c.-14C>T mutation in the IFITM5 gene." (PMID 36289625, 2022). "In 2012, a heterozygous mutation (c.-14C>T) in the 5’-untranslated region (UTR) of the IFITM5 gene was identified as the main cause of OI type V, greatly simplifying the diagnosis, and in 2014, a c.119C>T mutation was identified, with minor differences in the phenotype." (PMID 36289625, 2022). "All nine subjects with OI type V were heterozygous for the c.-14C > T IFITM5 mutation." (PMID 24674092, 2014). "To understand the functional consequences of increased ERK activation, we next generated an in vitro cell culture model of OI type V that stably overexpressed the mutant Ifitm5 in MC3T3 cells under doxycycline induction." (PMID 38885336, 2024). "Further studies in cells and zebrafish overexpressing mutant IFITM5 support our observation that activation of this pathway is involved in the mineralization defect and abnormal cartilage development in OI type V." (PMID 38885336, 2024). "To our knowledge, we report here the first conditional mouse model for OI type V that expresses mutant IFITM5 in 3 different cell types, i.e., limb mesenchymal cells, osteogenic cells, and chondrogenic cell lineages." (PMID 38885336, 2024). "Mutations in the IFITM5 gene, also called BRIL (bone-restricted IFITM-like protein), result in OI type V. Previous studies showed that the proportion of patients with OI type V can range from 5 to 10% of all cases." (PMID 36289625, 2022). "Sanger sequencing of the IFITM5 5’ UTR was performed in our cohort of subjects with a clinical diagnosis of OI type V. Clinical data was collated from referring clinicians." (PMID 24674092, 2014). "These compound mice could survive until adulthood, making it possible to explore the impact of mutant IFITM5 on bone homeostasis at adult stage and screen potential therapeutic targets for type V OI." (PMID 39908237, 2025).
osteogenesis imperfecta type 5 (continued). "The cartilage phenotype correlates with the pathology reported in patients with OI type V. Surprisingly, expression of mutant Ifitm5 in mature osteoblasts caused no obvious skeletal abnormalities." (PMID 38885336, 2024). "The biochemical mechanisms whereby mutated IFITM5 protein causes the skeletal pathology in OI type V are not well understood." (PMID 38885336, 2024). "The A subfamily is composed of the IFN-inducible and antiviral IFITM1, 2 and 3, as well as of IFITM5 and IFITM10, which are not IFN regulated and that in the case of IFITM5 are associated to Osteogenesis imperfecta type V, a bone-related genetic disease." (PMID 35396335, 2022). "We propose screening all patients without pathogenic variants in the COL1A1 and COL1A2 genes for the presence of pathogenic variants in the IFITM5 gene, even if they do not have the typical clinical symptoms of OI type V." (PMID 36289625, 2022). "This mutation creates an alternative start codon and has been shown in a eukaryotic cell line to result in a longer variant of IFITM5, but its expression has not previously been demonstrated in bone from a patient with OI type V." (PMID 24674092, 2014). "Our data support the hypothesis that the phenotype of OI type V results specifically from expression of a mutant, longer form of IFITM5 by osteoblasts." (PMID 24674092, 2014). "Through whole exome sequencing, two groups recently identified a single point mutation (c.-14C > T) in the 5’ untranslated region (UTR) of the gene encoding interferon-induced transmembrane protein 5 (IFITM5, also known as Bril) as the cause of OI type V (GenBank ID rs373183215)." (PMID 24674092, 2014).
osteosarcoma (6 papers, 2019 to 2026). A usually aggressive malignant bone-forming mesenchymal neoplasm, predominantly affecting adolescents and young adults. "The exact mechanism by which IFITM5 promotes the development and progression of osteosarcoma is still not fully understood." (PMID 38966281, 2024). "In particular, several studies have shown that IFITM5 is overexpressed in osteosarcoma and also it was reported that the overexpression of IFITM5 has been shown to promote the growth and invasion of osteosarcoma cells in vitro and in vivo." (PMID 38966281, 2024). "IFITM5 (Interferon-induced transmembrane protein 5) gene was overexpressed in osteosarcoma samples compared to normal samples." (PMID 38966281, 2024). "Overall, while more research is needed to fully understand the role of IFITM5 in bone cancer, these findings suggest that IFITM5 may be a potential target for the development of new treatments for osteosarcoma and other bone cancers." (PMID 38966281, 2024). "IFITM5, MMP13, PANX3, and MAGEA6 were some of the most overexpressed genes in osteosarcoma samples, while SLC4A1, HBA1, HBB, AQP7 genes were some of the top downregulated genes." (PMID 38966281, 2024). "Furthermore, IFITM5 is overexpressed in abnormal bone hyperplasia in rat primary osteoblasts, UMR106 rat osteosarcoma cells, human primary osteoblasts and Saos-2 human osteosarcoma cells." (PMID 36759884, 2023).
viral infection (3 papers, 2017 to 2024). "For the first time, we have identified new CRS-related genes such as ADGRG7, probably reflecting cellular-adhesion elements, LACRT, IBSP, MEPE, and IFITM5, probable antimicrobial genes with a potential role in viral infections." (PMID 36982612, 2023). "Our study has shown upregulated bone-homeostasis genes—human bone sialoprotein gene IBSP (generally upregulated), extracellular phospoglycoprotein MEPE, and interferon-induced transmembrane protein 5 IFITM5 (both upregulated only in CRSsNP), which may play a potential role in viral infection." (PMID 36982612, 2023).
Camurati-Engelmann disease (1 paper, 2021). Camurati-Englemann disease (CED) is a rare, clinically variable bone dysplasia syndrome characterized by hyperostosis of the long bones, skull, spine and pelvis, associated with severe pain in the extremities, a wide-based waddling gait, joint contractures, muscle weakness and easy fatigability. "A total of 7/47 probands suspected with OI carried variants in 6 disease-causing genes, namely, 1 IFITM5, 1 CRTAP, 2 BMP1, 1 PLS3, and 1 COL1A2 (c.432 + 4_432 + 7delAGTA was ignored previously), and 1 case of Camurati-Engelmann disease with pathogenic variants in TGFβ-1, which was misdiagnosed." (PMID 34557487, 2021).
dysplasia (1 paper, 2025). A usually neoplastic transformation of the cell, associated with altered architectural tissue patterns. "The other two cases were OI type 5, IFITM5-related, (OMIM#610967), observed in fetus 20 with severe angular deformity of the femurs, lower legs, and forearms and a molecularly unsolved gracile bone dysplasia seen in fetus 29, which is discussed further below." (PMID 40500351, 2025).
fibrodysplasia ossificans progressiva (1 paper, 2014). Fibrodysplasia ossificans progressiva (FOP) is a severely disabling heritable disorder of connective tissue characterized by congenital malformations of the great toes and progressive heterotopic ossification that forms qualitatively normal bone in characteristic extraskeletal sites. "In addition, given the transmembrane location of IFITM5 it may be a potential therapeutic target for other bone disorders such as fibrodysplasia ossificans progressiva and other forms of ectopic ossification." (PMID 24674092, 2014).
hyperlipidaemia (1 paper, 2024).
neuroblastoma (1 paper, 2022). Neuroblastoma (NB) is the most common solid, extracranial childhood tumor. "The IFITM family (in humans, five IFITM members: IFITM1, IFITM2, IFITM3, IFITM5, and IFITM10; in mice, seven Ifitm members: IFITM1, IFITM2, IFITM3, IFITM5, IFITM6, IFITM7, IFITM10) was first discovered as interferon-induced genes in human neuroblastoma cells." (PMID 36012150, 2022).
scoliosis (1 paper, 2023). A congenital or acquired spinal deformity characterized by lateral curvature of the spine. "We found that patients with COL1A1 and COL1A2 genotypes were strongly biased towards having mild or no scoliosis at all, whereas patients with pathogenic variants on IFITM5, WNT1 and other recessive genes did not display such a pattern." (PMID 37730650, 2023). "For the 20 patients with IFITM5 mutation, scoliosis severities were not more biased towards the non-scoliotic or mild groups." (PMID 37730650, 2023). "Patients with either COL1A1 and COL1A2 were strongly biased toward having mild or no scoliosis, whereas patients with mutations in IFITM5, WNT1 and other recessive genes were more evenly distributed among the four outcome grades." (PMID 37730650, 2023).
infection (5 papers, 2015 to 2024). The state of being infected such as from the introduction of a foreign agent such as serum, vaccine, antigenic substance or organism. "The expression levels of IFITM5 were found to be increased by approximately 5-fold at one day post infection, indicating the induction of these genes during the infection." (PMID 39315180, 2024). "We observed that Ifitm1, Ifitm2, Ifitm3, Ifitm5 and Ifitm6 were highly upregulated during NF1_LV infection while only Ifitm1, Ifitm3, Ifitm6 were upregulated during NF45_HV exposure and at a lower level." (PMID 39735262, 2024). "Antiviral genes, including IFNA, IFNG, MX1, IFITM1, IFITM3, and IFITM5, were upregulated in response to infection." (PMID 25505077, 2015).
tumor (2 papers, 2019 to 2023). "Correlation analysis was performed to further identify the relationship between tumor subtypes and IFITM5." (PMID 36759884, 2023).
IFITM5 also shares sentences with these, for which no sentence is quoted: bone disorder (3 papers); cancer (2); blepharoptosis (1); bone cancer (1); cholelithiasis (1); craniosynostosis (1); epidermolysis bullosa (1); exophthalmos (1); Hydrocephalus (1); hypophosphatasia (1); Obesity (1); osteoporosis (1); primary hyperoxaluria type 2 (1); Tricuspid regurgitation (1).